ZNF610 (zinc finger protein 610)
Description:
May be involved in transcriptional regulation.
Synonyms: FLJ36040
Tractability: PROTAC: UniProt records ubiquitination sites on it; ubiquitination databases record sites on it.
Gene: Protein-coding gene on chromosome 19 (52,336,243 to 52,367,778, forward strand). Ensembl gene ENSG00000167554.
Subcellular location: Nucleus
Subcellular location (Human Protein Atlas): Nucleoplasm
Pathways (Reactome):
Gene expression (Transcription): Generic Transcription Pathway; Regulation of endogenous retroelements by KRAB-ZFP proteins
Gene Ontology:
Molecular function: DNA-binding transcription factor activity, RNA polymerase II-specific; RNA polymerase II cis-regulatory region sequence-specific DNA binding
Biological process: regulation of transcription by RNA polymerase II; regulation of DNA-templated transcription
Cellular component: nucleus
Genetic constraint (gnomAD): Loss-of-function variants: 14 observed, 15.05 expected, observed/expected ratio (o/e) 0.93, 90% interval 0.61 to 1.45. The upper end of that interval is the gene's LOEUF score, 1.45, which puts it in group 5 of 6, group 1 being the genes least tolerant of losing a copy. Missense variants: 522 observed, 575.79 expected, observed/expected ratio (o/e) 0.91, 90% interval 0.84 to 0.98. Synonymous variants: 182 observed, 196.32 expected, observed/expected ratio (o/e) 0.93, 90% interval 0.82 to 1.05.
Homologues: Orthologues: chimpanzee ZNF610 (99% identical), mouse Zfy1 (19% identical), rat Zfy1 (18% identical), mouse Zfy2 (18% identical), tropical clawed frog zfx (18% identical), zebrafish zfx (17% identical). Paralogues in human: ZNF480 (70% identical), ZNF583 (40% identical), ZSCAN20 (37% identical), ZNF570 (36% identical), ZNF551 (34% identical), ZNF256 (34% identical), ZNF549 (34% identical), ZNF587B (34% identical), ZNF304 (34% identical), ZNF792 (33% identical), ZNF79 (33% identical), ZSCAN2 (32% identical), and 26 more.
Diseases named in the same sentence as ZNF610 in open-access papers:
ZNF610 is named in the same sentence as 1 disease in open-access papers, as found by Europe PMC text mining. Sharing a sentence is not in itself a finding about the gene and the disease.
ZNF610 shares sentences with these, for which no sentence is quoted: glaucoma (1 paper).